SOD1 (superoxide dismutase 1)
Diseases named in the same sentence as SOD1 in open-access papers (continued):
Sharing a sentence is not in itself a finding about the gene and the disease.
atherosclerosis (90 papers, 2008 to 2026). A disease characterized by the build-up of fatty material and calcium deposition in the arterial wall resulting in partial or complete occlusion of the arterial lumen. "SOD enzymes-SOD 1 being the major intracellular SOD- are part of the antioxidant defense system, implicated in lipid peroxidation and progression of atherosclerosis correlated with oxidative stress." (PMID 39469122, 2024). "Three cuproptosis-related genes—SLC31A1, SLC31A2 and SOD1 were screened out as diagnostic biomarkers for atherosclerosis." (PMID 37324184, 2023). "They found that an increase in serum SOD-1 levels was associated with decreased renal function with aging and atherosclerosis." (PMID 32823917, 2020). "Some of them demonstrated that the SOD1 level was higher in the serum of CKD patients compared to healthy controls, and it was associated with decreased renal function and atherosclerosis." (PMID 38389898, 2024). "As the results of our study revealed, lower expression of SOD1 in atherosclerosis plaques suggested activated oxidative stress in the process of atherosclerosis." (PMID 37324184, 2023). "The area under curve (AUC) of SLC31A1, SLC31A2 and SOD1 for the diagnosis of atherosclerosis was 0.800, 0.779 and 0.798 respectively in the GSE28829 dataset, with SLC31A1 demonstrating good diagnostic performance." (PMID 37324184, 2023). "The AUC of these three cuproptosis-related biomarkers for atherosclerosis was 0.736, 0.838 and 0.848 respectively in the GSE100927 dataset, with SLC31A2 and SOD1 performing good diagnostic value." (PMID 37324184, 2023). "In the training dataset GSE97210, SLC31A1, ATP7A, SLC31A2, UBE2D1, CP and FDX1 were highly expressed while LOXL2, COA6 and SOD1 were lowly expressed in the atherosclerosis group as showed in the bar charts." (PMID 37324184, 2023). "Oxidative damage leads significantly to the progression of atherosclerosis, and superoxide dismutase 1 (SOD 1) reduces the expressions of oxidative stress-related genes and the risk of atherosclerosis." (PMID 35801004, 2022). "SOD1 is a vasoprotective enzyme which ameliorates atherosclerosis in the aortae of SOD1 transgenic mice." (PMID 33080110, 2020). "Studies in apoE-/- mice showed that decrease of aortic content of F2-isoprostanes and alleviation of atherosclerosis occurred in response to overexpression of catalases in combination with SOD-1." (PMID 32245238, 2020). "Elevated SOD1 activity confers protection against acute or chronic oxidative injury, including atherosclerosis." (PMID 27830142, 2016). "Further studies show that blueberry supplementation attenuated atherosclerosis by upregulating expression of the antioxidant enzymes SOD1, SOD2, GSR, and thioredoxin reductase- (TR-) 1 in ApoE deficient mouse models of atherosclerosis." (PMID 23691264, 2013). "Findings from studies examining the antioxidant enzymes (SOD1, GPx, and HO-1) modulated by ROS in TGF-β-induced inflammatory responses provide valuable insights into the complex mechanisms underlying the pathogenesis of atherosclerosis." (PMID 40066126, 2024). "Consequently, SLC31A1, SLC31A2 and SOD1 were regarded as three hub cuproptosis-related biomarkers in atherosclerosis." (PMID 37324184, 2023). "In apoE-/- mice, overexpression of both SOD1 and catalase, which can degrade hydrogen peroxide, reduced atherosclerosis, while overexpression of SOD1 alone, on the contrary, could enhance the pathology development." (PMID 32245238, 2020). "In summary, we identified three hub cuproptosis-related genes—SLC31A1, SLC31A2 and SOD1 and construct a possible ceRNA network and a transcription factor regulation network in the molecular mechanism of atherosclerosis, providing new insights into cuproptosis and atherosclerosis." (PMID 37324184, 2023).
atherosclerosis (continued). "In rat atherosclerosis PCR array, Abca1, Bax, Bcl2, Bcl2a1, Cd44, Fabp3, Hbegf, Lypla1, Ptgs1, Selplg, Tgfb2, Tnc, and Vegfa had reverse trend between WT and MU groups, while the trends of Bcl2l1, Bid, Birc3, Cxcl1, Fas, Fn1, Itga2, Itga5, Lif, Nfkb1, Nr1h3, Ppard, and Sod1 were consistent." (PMID 34545275, 2021). "Indeed, SOD1 overexpression alone may increase the extent of atherosclerosis; however, overexpression of catalase, in addition to SOD1, reduces atherosclerosis in ApoE−/− mice." (PMID 31354915, 2019). "Also, from another point of view, further applications of SOD1 secreting stem cells are their utility in the cardiovascular diseases, including ischemic heart disease, cerebrovascular disease, atherosclerosis, and other related problems, such as myocardial infarction." (PMID 30140407, 2018). "Consistently, the atherosclerosis plaques showed significantly higher expression of SLC31A1, SLC31A2 and lower expression of SOD1 than the normal intimae." (PMID 37324184, 2023). "In the vascular wall, oxidative stress is counteracted by several antioxidant enzyme systems including SOD1 and CAT; indeed, in ApoE KO mice, the overexpression of both genes reduced atherosclerosis." (PMID 32824091, 2020). "The mechanisms by which metformin inhibits atherosclerosis can be categorized into three main types: activation of autophagy, disruption of angiotensin-II-type-1 receptor (AT1R), and upregulation of antioxidant enzyme superoxide dismutase 1 (SOD1)." (PMID 38255895, 2024). "One proposed mechanism by which these berries attenuated atherosclerosis is increased antioxidant capacity by the upregulation of glutathione reductase (GSR) and Trx 1 (blueberry), SOD1 and SOD2 (blueberry and hawthorn berry), and GPx1 and paraoxonase-1 (PON1) (acai berry)." (PMID 32664664, 2020). "Five of eight proteins are Peroxiredoxin-1 (Prdx-1), superoxide dismutase (SOD1), haemopexin (HPX), 60 kDa heat shock protein (HSP60), and serine/threonine-protein phosphatase (CPPED1), all of which are related to lipid peroxidation and atherosclerosis." (PMID 27536279, 2016). "The upregulation of SOD1, CAT, MIF, and PPARγ observed in this study is in line with previous works, which have demonstrated the antioxidant proprieties of a diet rich in nuts, related to the regulation of cellular pathways of atherosclerosis, inflammation, and oxidative stress." (PMID 31354906, 2019).
depression (90 papers, 2013 to 2026). "Collectively, these observations highlight the complexity of targeting SOD1 and underscore the imperative for tissue-specific therapeutic strategies in depression management." (PMID 41601681, 2026). "Impact of nightly sleep duration on serum level of PAB and SOD1 in subjects with depression and anxiety separately, respectively adjusted for age and sex in Mashhad stroke and heart atherosclerotic disorders, Iran, 2010–2020." (PMID 37744415, 2023). "Expressions of CAT and SOD1 are also decreased in postmortem brain regions of individuals with AD and depression compared to those with AD alone, suggesting that the stress-related disorder of depression is indeed a risk factor for AD." (PMID 36453495, 2023). "Interestingly, there are antagonists or inhibitors for the products of three DEGs that are up-regulated in isolation-reared rats and patients with schizophrenia (Snca), depression (Sod1) or both (Hrh3)." (PMID 39502833, 2024). "Expressions of SOD1, CAT, IGF2 and IGF2R also decreased in the postmortem brain regions of individuals with AD and depression compared those of AD, suggesting that the stress-related disorder of depression is indeed a risk factor for AD and exaggerates OS." (PMID 38338968, 2024). "Consequently, the primary objective of this population-based cross-sectional study was to investigate the impact of sleep duration on PAB, SOD1, anxiety, and depression." (PMID 37744415, 2023). "An increased expression of SOD1 may induce inflammation, which inflammation itself can contribute to depression/anxiety." (PMID 37744415, 2023). "By prioritizing UCP2, SOD1, HK2, NDUFS4, and NEU1, our findings highlight novel, immune-mediated pathways in depression and nominate promising targets for future diagnosis and therapeutic intervention." (PMID 41601681, 2026). "This study shows the effects of chronic administration of agomelatine on expression and the methylation status of Sod1, Sod2, Gpx1, Gpx4, Cat, Nos1, and Nos2 in the brain stricture and blood in the chronic mild stress (CMS) animal model of depression." (PMID 32545212, 2020). "Once Nrf2 is activated, Keap1 is released from Nrf2 and promotes nuclear translocation of Nrf2, activating the downstream target proteins HO-1, SOD1, GCLC, and GCLM, thus playing a key role in anti-inflammatory and anti-oxidative stress activities of depression." (PMID 40308754, 2025). "Therefore, we aim to assess the relationship between sleep duration, serum pro-oxidant/antioxidant balance (PAB) and superoxide dismutase 1 (SOD1) levels as markers of oxidative stress, anxiety, and depression." (PMID 37744415, 2023).
neuroblastoma (90 papers, 2006 to 2025). Neuroblastoma (NB) is the most common solid, extracranial childhood tumor. "Their expression was analyzed in a human in-vitro model of the disease, specifically in the human neuroblastoma cell line SH-SY5Y stably transfected with the SOD1 gene either WT or carrying the G93A mutation." (PMID 34356873, 2021). "A preclinical study showed that NAC (1 mM and 24 h) lowered mitochondrial ROS production, returned MTT reduction rate to control levels, and also increased ATP levels in human neuroblastoma SH-SY5Y cell lines carrying G93A SOD1 mutation." (PMID 33274002, 2020). "Alterations of mitochondria, associated with reduced mitochondrial membrane potential, have been reported also in mutated human SOD1(G37R) neuroblastoma cells and in SOD1(G93A) primary motoneurons." (PMID 31680811, 2019). "There are reports indicating that the physiological role of nuclear SOD1 is associated with the decrease in the DNA damage induced by ROS in yeast and in neuroblastoma SH-SY5Y cells." (PMID 31540440, 2019). "Fe homeostasis in SOD-1(G93A) ALS was further studied using transgenic neuroblastoma SH-SY-5Y cells stably transfected with WT SOD-1 or the G93A mutated human SOD-1 gene." (PMID 25100994, 2014). "Recent studies on ALS show that overexpression of the mitochondrial superoxide dismutase (SOD2) can decrease SOD1 associated cytotoxicity and cell death in human neuroblastoma cell line LAN5 expressing mutant SOD1." (PMID 24288463, 2013). "It was reported that in neuroblastoma cell lines, depletion of SOD1 caused early cytoskeletal alterations in the cells that ultimately activates pro-survival pathways." (PMID 21655261, 2011). "Recently, the toxicity of mutant SOD1 in neuroblastoma cells has been linked with increased levels of nitric oxide." (PMID 21603027, 2011). "Earlier studies have revealed that SOD1 is involved in the regulation of cellular cytoskeleton and siRNA-mediated depletion of SOD1 caused alterations in actin cytoskeleton in neuroblastoma cell lines." (PMID 21655261, 2011). "Here we demonstrate that activation of macrophages by the TLR2 agonist Pam3CSK4 can also cause neuronal death, and that neuroblastoma cells expressing G93A-SOD1 are more susceptible to the attack of activated immune cells than those expressing wild-type SOD1." (PMID 17997855, 2007). "To identify conditions which lead to the aggregation of mutant SOD1, we generated SK-N-SH human neuroblastoma cell lines that stably expressed FLAG-tagged human SOD1 encoding a leucine to valine substitution mutation (L84V) associated with FALS." (PMID 17925878, 2007). "Human neuroblastoma cells expressing the SOD1-G93A mutated protein (SH-SY5Y SOD1G93A cells) were incubated for 24 h with H2O2 (150 μM) in the absence, or presence, of GHS (1 μM), in order to study the protective effect of GHS against increased oxidative stress." (PMID 36674509, 2023). "In this in vitro study, we investigated potential protective effects of hexarelin and JMV2894 on human neuroblastoma cells overexpressing the SOD1-G93A mutated protein in order to ascertain whether these two GHSs could be candidates for the development of new drugs for the treatment of ALS." (PMID 36674509, 2023). "Bim silencing also decreased Bax recruitment to mitochondria and cytochrome c redistribution in a SOD1 murine neuroblastoma cell line." (PMID 38491246, 2024). "Our group recently found that SOD1 interaction with muscarinic M1 receptor, in human neuroblastoma SK-N-BE cells, can activate ERK1/2 and AKT kinases in a dose/time-dependent manner." (PMID 37760050, 2023). "The aggregation property and cellular toxicity of SOD1-D92G were assessed in mouse neuroblastoma Neuro2a cells transfected with pSOD1-D92G-EGFP vector." (PMID 35879519, 2022).
neuroblastoma (continued). "In this context, the expression of mutant SOD1 in a human neuroblastoma cell line (SH-SY5Y) induces a decrease in OPA1 expression, probably due to the oxidative damage induced by the presence of mutant SOD1 and the increase of DRP1 (P-DRP1 s616)." (PMID 35787292, 2022). "Since there was no previously available report to know if SOD1T54R was aggregation-prone, we conducted confocal fluorescence microscopy studies to find the expression and self-aggregation properties of SOD1T54R and SOD1 in human neuroblastoma (IMR-32) cells." (PMID 35492906, 2020). "For this study, we used the N2A cell line, mouse neuroblastoma, and SOD1-G93A mice and control mice." (PMID 33065963, 2020). "For instance, CST3 increases neuron viability by inhibiting autophagy and cathepsin B (Cat B) in Cu/Zn-superoxide dismutase (SOD1)-mutant, or cytotoxicity-exposed neuroblastoma cell lines and primary cultured motor neuronal cells." (PMID 32733872, 2020). "Our results also indicate that the pre-exposure of neuroblastoma cells to RF strongly limited the MD-dependent decrease in both gpx1/sod1 (0.72) and gpx1/sod2 (0.82) ratios." (PMID 30185877, 2018). "Successively, we showed that SOD1 in human neuroblastoma SK-N-BE cells is exported through a microvesicular secretory pathway that is impaired by brefeldin-A (BFA), and by 2-deoxyglucose, and sodium azide, which reduces ATP intracellular pool." (PMID 27965593, 2016). "We have focused on changes relating to the expression of mutant human SOD1 in comparison with both the expression of wild-type human SOD1 and the untransfected line, in order to limit the impact of the neuroblastoma phenotype on interpretation." (PMID 25963727, 2016). "Aggregated recombinant SOD1 can be taken up by neuroblastoma cells, and primary or permanent microglia cell cultures." (PMID 24282413, 2013). "Secretion of endogenous SOD1 has been reported for a variety of different cell lines, including fibroblasts, neuroblastoma, motor neuron cell lines and primary spinal cord cultures." (PMID 24282413, 2013). "In the murine neuroblastoma cell line, Neuro2a, bearing mutant SOD1 inclusions, indicators of both ER stress and apoptosis are expressed." (PMID 22523592, 2012). "Using human neuroblastoma SH-SY5Y cells we demonstrated a strong linkage of PSA/NPEPPS to SOD1 accumulation/clearance." (PMID 21548977, 2011). "Our in vitro results with murine neuroblastoma cell line overexpressing SOD1 demonstrated an increase in PSA/NPEPPS protein expression." (PMID 21548977, 2011). "There are two reports describing the expression of mutant SOD1 fused to GFP in mouse neuroblastoma N2a cells." (PMID 22094223, 2011). "More recently, siRNA-mediated knockdown of PDI was also shown to increase mutant SOD1 inclusion formation in neuroblastoma cells, confirming the importance of PDI in modulating mutant SOD1 aggregation." (PMID 21603027, 2011). "In mouse neuroblastoma cell line N1E-115 transfected with mouse SOD1 overexpression vectors pCMV6-XL-SOD1, mouse PSA/NPEPPS protein expression was upregulated up to 4-fold (p = 0.0001)." (PMID 21548977, 2011). "Our above in vitro experiments in human neuroblastoma cell line support the recent observation that PSA/NPEPPS is a modulator of SOD1 protein abundance in 293A cells." (PMID 21548977, 2011). "An in-vitro model to study the cellular alterations associated with mutations of SOD1 was constructed by transfection of the human neuroblastoma cell line SH-SY5Y with G93A-SOD1." (PMID 17997855, 2007). "First, ER stress in neuroblastoma cells expressing mutant SOD1 results in SOD1- and ubiquitin-immunopositive LHIs, compatible with LBHI/Ast-HI, composed of granule-coated fibrils approximately 15–25 nm in diameter and granular materials." (PMID 17925878, 2007).